TFEB (transcription factor EB)
Diseases named in the same sentence as TFEB in open-access papers (continued):
Sharing a sentence is not in itself a finding about the gene and the disease.
Parkinson disease (continued). "Moreover, the transcription factor EB (TFEB) has been described as a molecular target to treat neurodegenerative disorders such as AD, Parkinson’s disease, or Huntington’s disease." (PMID 35563589, 2022). "For example, TFEB improved the progression of Parkinson’s disease and liver steatosis." (PMID 33995096, 2021). "In addition, overexpression of TFEB has been reported to be beneficial in numerous disease models via clearance of aggregated protein (e.g., tau in Alzheimer's, α-syn in Parkinson's, and HTT in Huntington's)." (PMID 33224433, 2020). "There was a transient increase of TFEB in the nuclear of primary microglia, suggesting a compensatory reaction of microglia to Aβ, and then followed by a sustained efflux of TFEB from the nucleus, which was consistent to the finding in Parkinson's disease rat model (Decressac and Björklund, 2013)." (PMID 28769785, 2017). "Other studies have reported that TFEB-mediated autophagy helps to reduce protein aggregation while protecting neurons from neurotoxicity in the case of neurodegenerative diseases, such as Parkinson's disease and Huntington's disease." (PMID 27195074, 2016). "For instance, the parkin Q311X mutation present in a subset of Parkinson's disease patients reduces the turnover of parkin‐interacting substrate (PARIS), relieving its transcriptional repression of PGC1‐(alpha), and thus downregulating TFEB and suppressing TFEB‐facilitated mitophagy." (PMID 37728021, 2023). "TFEB translocation from cytoplasm to nucleus has been shown to increase the number of lysosomes and promote protein clearance under various conditions of aliments involved in protein misfolding, including Huntington's disease, Parkinson's disease and Pompe's disease." (PMID 28769785, 2017).
Hepatic steatosis (38 papers, 2019 to 2025). Steatosis is a term used to denote lipid accumulation within hepatocytes. "TFEB deficiency in PTECs caused mitochondrial dysfunction and increased circulating FFAs, which can lead to systemic metabolic disorders such as hepatic steatosis and adipocyte hypertrophy." (PMID 39699959, 2024). "Expanding on these findings, a study on hepatocytes treated with palmitic acid, an in vitro fatty liver disease model, revealed a decrease in nuclear TFEB levels and its downstream target genes encoding for lysosomal CTSB and LAMP1." (PMID 38978979, 2024). "Overall, our study elucidates the critical role of TFEB in hepatic lipid homeostasis and shows that loss of TFEB function contributes to the pathogenesis of diet-induced fatty liver." (PMID 35625599, 2022). "In addition, it was recently shown that loss of Hif-2α in macrophages increases TFEB activation in KCs and reduces liver steatosis and damage." (PMID 41665896, 2025). "Taken together, these results suggest that MAT1A deficiency contributes to hepatic cysteine and CoA deficiency and susceptibility to hepatic steatosis, and selective hepatic cysteine enrichment and stimulation of CoA synthesis are largely mediated by TFEB induction of hepatic MAT1A." (PMID 36171419, 2022). "Therefore, TFEB activation may be an important marker for determining the degree of hepatic steatosis in NAFLD patients and associated with decreased autophagy activity." (PMID 39758315, 2024). "Pharmacologic inhibition of mTOR by torin-1, a novel mTOR inhibitor, could reverse the inhibition of TFEB, liver steatosis, and liver injury in chronic-plus-binge alcohol treatment, suggesting a potential association between the mTOR pathway and TFEB inhibition by alcohol." (PMID 31614437, 2019). "Another recent study also confirmed that the beneficial effects of fenofibrate on hepatic steatosis, IR, and gut microbiota modulation depend on TFEB-mediated autophagy." (PMID 40906106, 2025). "KC preservation through TFEB induction reduced liver steatosis with HFHS diet via mechanisms that were dependent on macrophage lysosomal lipolysis and mitochondrial fatty acid oxidation." (PMID 41665896, 2025). "We discovered that TFEB-overexpression rescues KC death in vivo, augments their lipid uptake and metabolism, and reduces liver steatosis after MASLD induction." (PMID 41665896, 2025). "The compound MSL, also known as 4-sulfonyl-5-methylthio-2-phenyloxazole, was discovered to activate TFEB and effectively ameliorate adipose inflammation, hyperglycaemia, hepatic steatosis, and obesity in diabetic mice with the ob/ob phenotype." (PMID 40354374, 2025). "Nuciferine targets HBXIP to inhibit mTORC1 and activate the TFEB-mediated autophagy-lysosome pathway, thereby further improving hepatic steatosis." (PMID 41561171, 2025). "NOB, a citrus flavonoid, alleviates hepatic steatosis mainly through transcription factor EB (TFEB)-mediated lysosomal biogenesis and lipophagy." (PMID 39858534, 2025). "In NAFLD patients, hepatic steatosis leads to TFEB phosphorylation mainly occurring in the cytoplasm." (PMID 39758315, 2024). "Liraglutide ameliorates hepatic steatosis by inducing activation of the TFEB-mediated ALP through modulation of LC3-II and SQSTM1/P62 autophagy substrates expression levels." (PMID 39175576, 2024). "In summary, this study demonstrates that desloratadine promotes clearance of lipids and ameliorates hepatic steatosis through TFEB-mediated autophagy-lysosome pathway activation." (PMID 39359254, 2024). "Beyond the liver gluconeogenesis induced by MET, it has been revealed that an additional protective effect against hepatic steatosis and IR can be exerted through the transcription factor EB‐autophagy pathway." (PMID 39554295, 2024). "A high-fat diet-induced hepatic steatosis mouse model was used to assess the effects of the identified TFEB agonist desloratadine on lipid clearance." (PMID 39359254, 2024).
Hepatic steatosis (continued). "Second, both increased hepatic APOA4 synthesis due to hepatic steatosis and decreased APOA4 degradation in TFEB-deficient PTECs are likely the presumptive mechanism of APOA4 amyloidosis." (PMID 39699959, 2024). "Altogether, these findings demonstrate desloratadine ameliorates hepatic steatosis through activating the TFEB-mediated autophagy-lysosome pathway, thus desloratadine has an exciting potential to be used to treat fatty liver disease." (PMID 39359254, 2024). "Inhibition of AMPK resulted in TFEB nuclear localization, inhibited liver autophagy, and contributed to the development of hepatic steatosis." (PMID 38526033, 2024). "The deficiency of TFEB in hepatocytes leads to a decrease in lipid metabolism, exacerbating metabolic diseases such as HFD induced hepatic steatosis and insulin resistance." (PMID 39758315, 2024). "Second, Liraglutide activated autophagic flux and attenuated hepatic steatosis through the TFEB-mediated autophagy-lysosomal pathway." (PMID 37079136, 2023). "TFEB can also be activated by other treatments for hepatic steatosis, including ezetimibe, procyanidin B2, formononetin, liraglutide, fenofibrate, and metformin." (PMID 35625599, 2022). "Emerging evidence continues to demonstrate the role of TFEB in the pathogenesis of liver steatosis and NAFLD." (PMID 35625599, 2022). "Overall, evidence strongly suggests that TFEB is a promising therapeutic target for improving hepatic steatosis." (PMID 35625599, 2022). "The magnitude of TFEB-mediated hepatic TG reduction was attenuated but not fully abolished upon MAT1A knockdown, which is expected since TFEB is known to lower hepatic steatosis via other mechanisms." (PMID 36171419, 2022). "By activating AMPK, formononetin promotes nuclear translocation of key regulator transcription factor EB (TFEB) in lysosomal organisms, leading to autophagosome–lysosomal fusion and lipid phagocytosis, and alleviates hepatic steatosis." (PMID 35035928, 2022). "In contrast, restoration of autophagy by overexpression of Atg14, TFEB, or deletion of rubicon improved hepatic steatosis and injury, as well as attenuated cellular stress." (PMID 34786524, 2021). "Metformin treatment significantly reverses the activity of TFEB, and the protective effect of metformin against hepatic steatosis and insulin resistance is dependent on TFEB." (PMID 34366846, 2021). "For example, TFEB activates autophagy to indirectly inhibit liver steatosis and against weight gain in obesity." (PMID 33679452, 2021). "Apart from T3, other TH metabolites such as T2 also mediate hepatic autophagy via induction of TFE3 and TFEB transcription factors to reduce hepatic steatosis in rodent models of NAFLD." (PMID 34786524, 2021). "More recently, hepatic TFEB overexpression has been shown to induce the PGC1α/PPARα pathway to promote fatty acid oxidation and prevent chronic high-fat diet-induced hepatic steatosis in mice." (PMID 32681035, 2020). "After silencing TFEB, the liraglutide-mediated promotion of lysosome biogenesis and alleviation of hepatic steatosis were attenuated." (PMID 33330497, 2020). "Recently, the suppression of transcription factor EB (TFEB)-mediated lysosome biogenesis and autophagy was demonstrated to promote chronic ethanol uptake-induced hepatic steatosis and liver injury." (PMID 30642133, 2019). "Inhibition of AMPK completely blocked the effects of CAT on TFEB nuclear localization, hepatic autophagy, and liver steatosis." (PMID 31697646, 2019). "Dysregulation of TFEB activity may contribute to the development of several diseases, including hepatic steatosis, neurodegenerative diseases, cancer, and inflammatory diseases." (PMID 40636317, 2025). "TFEB also suppresses SREBP1c to alleviate hepatic steatosis." (PMID 40564141, 2025). "We next investigated the impact of TFEB induction in KCs on liver steatosis." (PMID 41665896, 2025).
Hepatic steatosis (continued). "Thus, KCs are poorly adapted to the lipid-rich environment of MASLD but can be programmed by TFEB induction to enhance lipid handling and improve hepatic steatosis." (PMID 41665896, 2025). "Sesamin restores impaired mitochondrial morphology and function by activating the TFEB pathway, and significantly alleviates lipid accumulation induced by 9-trans-C18:1 in L02 cells, which may exert preventive or protective effects on hepatic steatosis." (PMID 39758315, 2024). "Furthermore, in mice fed a Western diet, ASBT inhibitor significantly improves hepatic steatosis in a manner correlated with the increase in nuclear TFEB in the liver." (PMID 35625599, 2022). "Interestingly, this study also shows that withdrawal of alcohol can restore nuclear TFEB contents and thereby reverse hepatic steatosis." (PMID 35625599, 2022). "In addition to mouse models, TFEB is also altered and involved in alcohol-induced hepatic steatosis in male Wistar rats given an alcohol liquid diet for six weeks." (PMID 35625599, 2022). "Furthermore, in mouse models of obesity, suppression of TFEB, and Atg7 by liver-specific gene deletion facilitate liver steatosis and weight-gain." (PMID 33679452, 2021). "A recent study shows that digoxin, ikarugamycin, and alexidine dihydrochloride may promote TFEB nuclear translocation, thereby inhibiting IR and hepatic steatosis, and enhancing the autophagic flux in mice fed an HFD." (PMID 34366846, 2021). "To test whether the activation of autophagy mediated by TFEB was involved in the alleviation of an excessive lipid accumulation and IR in HFD-fed mice, we measured the hepatic steatosis level using H&E and Oil red O staining after the knockdown of TFEB." (PMID 34366846, 2021). "Importantly, studies on hepatic biopsies of patients with non-alcoholic fatty liver disease revealed that the lower the activity of TFEB, the more serious the liver steatosis and lipid aggregation." (PMID 33679452, 2021). "However, the role of TFEB in hepatic steatosis is not well understood." (PMID 34366846, 2021). "Our data demonstrate that harnessing lysosomal lipid metabolism through TFEB induction promotes KC fitness in MASLD, leading to improved liver steatosis." (PMID 41665896, 2025). "We report here that activating TFEB in resident KCs during MASLD reprograms their metabolism, resulting in reduced liver steatosis and improved KC survival." (PMID 41665896, 2025). "In summary, we demonstrate that TFEB protects KCs in MASLD, reduces liver steatosis, and preserves liver filtration." (PMID 41665896, 2025). "There are also studies revealing that TFEB promotes nuclear translocation by activating the AMPK pathway and alleviates hepatic steatosis in mice fed with HFD." (PMID 39758315, 2024). "Collectively, our study suggests that AO ameliorates hepatic steatosis via AMPK/autophagy- and AMPK/TFEB-mediated suppression of lipid accumulation, which opens new opportunities for pharmacological treatment of NAFLD and associated complications." (PMID 35087411, 2021). "Recent studies have revealed that TFEB nuclear translocation was promoted by pharmacologically activating the AMPK pathway and eventually alleviated hepatic steatosis in HFD-fed mice." (PMID 33330497, 2020). "In conclusion, the results of this study suggest that CAT attenuates hepatic steatosis and lipotoxicity by inducing autophagy via AMPK activation and subsequent nuclear translocation of TFEB in a mouse model." (PMID 31697646, 2019). "Furthermore, catalpol and aurantio-obtusin have been shown to alleviate hepatic steatosis by activating AMPK and TFEB-dependent autophagy." (PMID 40906106, 2025). "Furthermore, liraglutide suppressed hepatic steatosis via the restoration of autophagy, in particular the GLP-1R- transcription factor EB (TFEB)-mediated autophagy-lysosomal pathway." (PMID 36230573, 2022).
Hepatic steatosis (continued). "Despite the absence of hepatic steatosis after 1-week WD challenge, hepatic β-hydroxybutyrate, a marker of fatty acid oxidation, was higher in TFEB overexpression groups." (PMID 36171419, 2022). "On the other hand, hepatic TFEB overexpression prevents hepatic and plasma cholesterol elevation independent of hepatic steatosis, which links TFEB-induction of bile acid synthesis to maintenance of cholesterol homeostasis." (PMID 32681035, 2020). "In a NAFLD mouse model and a PA-induced HepG2 cell model, liraglutide has been observed to alleviate hepatic steatosis by modulating the expression of autophagy substrates LC3-II and SQSTM1/P62, thereby activating the autophagy-lysosomal pathway (ALP) regulated through the TFEB pathway." (PMID 39175576, 2024). "Our study found that ponatinib could effectively ameliorate hepatic steatosis, inflammation and fibrosis in MCD-induced NASH mice by enhancing autophagy through increasing TFEB expression, and thus ponatinib may be a promising drug for the treatment of NASH (Graphical abstract)." (PMID 39840105, 2024).
atherosclerosis (37 papers, 2016 to 2026). A disease characterized by the build-up of fatty material and calcium deposition in the arterial wall resulting in partial or complete occlusion of the arterial lumen. "TFEB downregulation or deficiency can obviously affect the cellular phenotype in a physiologically relevant manner in settings including atherosclerosis, nonalcoholic fatty liver disease, cancer and neurodegeneration." (PMID 35045880, 2022). "In atherosclerosis models, trehalose can rescue autophagy-lysosomal dysfunction in foamy macrophages through TFEB overexpression, enhancing lipid phagocytosis and metabolism, reducing inflammation, and delaying plaque formation." (PMID 39881390, 2025). "Cur, a polyphenol derived from Curcuma longa, has been shown to mitigate atherosclerosis by promoting TFEB activation, enhancing autophagy, and reducing inflammation." (PMID 40426881, 2025). "Genetic or pharmacological activation of the TFEB-mediated autophagy–lysosome system has been shown to reduce atherosclerosis in animal models." (PMID 40076784, 2025). "The following sections discuss the involvement of TFEB in atherosclerosis, its role in vascular smooth muscle cell stability, and the therapeutic potential of pharmacological agents in enhancing TFEB activity." (PMID 40426881, 2025). "By upregulating genes involved in lysosomal stability and acidification, TFEB ensures the efficient degradation of cellular debris and prevents lysosomal rupture, which is a key driver of inflammatory responses in atherosclerosis and HF." (PMID 40426881, 2025). "Previous studies using LysM–Cre to drive TFEB overexpression in myeloid cells revealed protection against atherosclerosis, diet-induced obesity, and insulin resistance." (PMID 41665896, 2025). "Enhancing TFEB expression or activity in macrophages has been shown to attenuate lipotoxic cell death and reduce atherosclerosis in mice." (PMID 41665896, 2025). "In cardiovascular diseases, increased SNX10 expression stimulates lipid accumulation in macrophages via the AKT/TFEB signaling pathway, which contributes to atherosclerosis." (PMID 40426851, 2025). "Transcription factor EB (TFEB) is a master regulator of lysosome function and lipid metabolism, which has been shown to protect macrophages from lipid stress in atherosclerosis." (PMID 41665896, 2025). "In models of atherosclerosis and motor neuron degeneration, trehalose has been shown to boost autophagy by inducing TFEB overexpression." (PMID 39881390, 2025). "Excitingly, TFEB activation by trehalose occurs in a mTORC1-independent manner, making the use of trehalose to reverse atherosclerosis a promising therapeutic approach." (PMID 38433753, 2024). "TFEB is regulated by multiple signaling pathways and can modulate several processes that are important in atherosclerosis, including lipophagy, autophagy, lipolysis, and inflammation." (PMID 37239823, 2023). "Trehalose induces autophagy through lysosomal mediated TFEB, which can be used as a new drug choice for treating atherosclerosis, Motoneuron degeneration, cardiac remodeling and other diseases." (PMID 35531069, 2022). "Third, we delineated the involvement of the AMPK/TFEB signaling pathway in bromelain-conferred protection from hepatic lipid accumulation and atherosclerosis in apoe−/− mice." (PMID 36670934, 2022). "In view of its function, treatment with bromelain confers protection against oxidative stress and inflammatory responses, leading to the alleviation of the progression of atherosclerosis by activating TFEB to stimulate antioxidant generation." (PMID 36670934, 2022). "Recently, a growing body of studies have indicated that TFEB regulates the homeostasis of the cardiovascular system and confers protection from CVDs such as aortic aneurysms, cardiotoxicity, and atherosclerosis." (PMID 36670934, 2022). "TFEB overexpression also inhibits atherosclerosis plaques from the aspect of promoting lipid transport." (PMID 33679452, 2021).